EOMES (eomesodermin)
Diseases named in the same sentence as EOMES in open-access papers (continued):
Sharing a sentence is not in itself a finding about the gene and the disease.
lymph node metastasis (1 paper, 2013). "Authors demonstrated that the expression of EOMES (eomesodermin), a T-box transcription factor, was inversely correlated with the presence of lymph node metastasis at diagnosis and that was crucial in controlling the production of perforin by CD8+ CTLs and thus enhancing their cytotoxic activity." (PMID 24151976, 2013).
primary progressive multiple sclerosis (1 paper, 2025). A multiple sclerosis that is characterized by steady worsening of neurologic functioning, without any distinct relapses or periods of remission. "Frequencies of Eomesodermin+ Th cells could differentiate between patients with secondary and primary progressive multiple sclerosis and correlated with B-cells in secondary progressive multiple sclerosis." (PMID 41346466, 2025).
secondary progressive multiple sclerosis (1 paper, 2025). A multiple sclerosis with a clinical course characterized by a progressive accumulation of neurological disability, independent of relapses, following an initial relapsing-remitting (RR) phase. "Eomesodermin+ Th cells are associated with cytotoxicity, neuroinflammation and disease progression in secondary progressive multiple sclerosis." (PMID 41346466, 2025).
seminoma (1 paper, 2019). A radiosensitive malignant germ cell tumor found in the testis (especially undescended), and extragonadal sites (anterior mediastinum and pineal gland). "Furthermore, TCam-2-ΔSOX2/FOXA2 derived tumors stained positive for pluripotency and seminoma markers OCT3/4, SOX17, TFAP2C, and PRDM1/BLIMP1, but were negative for the differentiation-markers AFP and EOMES." (PMID 31130628, 2019).
Sepsis (1 paper, 2025). Sepsis is defined as life-threatening organ dysfunction caused by a dysregulated host response to infection. "Likewise, when focusing on TFs related to the regulation of cytotoxicity genes (TBX21, EOMES, JUN, and RUNX3), alterations are evident within the sepsis cells." (PMID 41208955, 2025).
vitiligo (1 paper, 2018). Generalized well circumscribed patches of leukoderma that are generally distributed over symmetric body locations and is due to autoimmune destruction of melanocytes. "Moreover, EOMES, a transcription factor characteristic for effector cytotoxic T cells and innate and innate-like virtual memory T cells, was increased in both vitiligo lesional and non-lesional skin (p < 0.001 and p < 0.001, respectively)." (PMID 30515176, 2018).
tumor (64 papers, 2012 to 2026). "Transforming growth factor–β is expressed in the majority of TMEs, which inhibits the tumor lytic response and causes the expression of eomesodermin (EOMES) lost, ultimately contributing to NK cell exhaustion." (PMID 40043109, 2025). "ID3, RDH10 and EOMES are transcription factors associated with a dysfunctional tumor-infiltrating T cell state." (PMID 36135194, 2022). "Mechanistically, Blimp1 enforced intratumoral Treg cells with a unique transcriptional program dependent on Eomesodermin (Eomes) expression; deletion of Eomes in Blimp1-deficient Treg cells restored tumor growth and attenuated anti-tumor immunity." (PMID 34798898, 2021). "Gene regulatory network analysis revealed that top regulators of Group 4 MB tumour cells include EOMES, SOX4, and SOX11." (PMID 41998565, 2026). "Tc1 is a subtype of CT8+ T with tumor-killing function, regulated by transcription factors EOMES and TBX21." (PMID 39076970, 2024). "Reduced T-BET and EOMES expression results in dysfunctional NK cells and failure to control tumor growth." (PMID 34630413, 2021). "In this study, we investigated the expression of EOMES transcription factor in tumor and T cells from PB and LN of CLL patients and its relation to T-cell exhaustion." (PMID 33731848, 2021). "In accordant with our observation using immunohistochemistry staining, the expression of EOMES was significantly decreased in tumour samples and stage IV HCC showed the lowest EOMES expression." (PMID 33325636, 2021). "To investigate the role of EOMES in T cells, we first examined the expression of EOMES in tumour and peritumoral samples of HCC in a cohort containing 384 patients with HCC." (PMID 33325636, 2021). "EOMES is an important transcriptional regulator of type I effector T cells, and plays key roles in the regulation of the tumor immune response." (PMID 33929972, 2021). "• Tumors from non-responders to monotherapy often express other immune checkpoints and higher gene expression profile of EOMES+, CD69+, CD45RO+ T cells is associated with greater tumor shrinkage in both therapies." (PMID 32265933, 2020). "We were intrigued by a reversal of tumor-induced downregulation of effector genes perforin, granzyme B and eomesodermin in the spleens and LN of tumor-bearing mice treated with bortezomib." (PMID 26431276, 2015). "There was a strong correlation between expression of EOMES, coding for eomesodermin, before and after treatment and survival, thus suggesting that CD8+ or NK cells anti-tumor cytotoxic responses would be associated with longer survival." (PMID 25170840, 2014). "Three genes, CD8A, CRTAM, and EOMES, were consistently upregulated in all six tumor types." (PMID 38488909, 2024). "EOMES is an important transcription factor that regulates the differentiation and function of effector T cells, and previous studies have shown that the survival of tumor patients is closely related to EOMES expression." (PMID 34980144, 2022). "Indeed, the anti-4-1BB increases the functional activity of tumor-specific CD8+ CTLs by inducing the expression of T-box transcription factor Eomesodermin (Eomes)." (PMID 36480493, 2022). "As low T-BET and EOMES expression levels in NK cells from tumor patients negatively impacts the anti-tumor effects, we here studied the effects of either T-BET or EOMES overexpression in cord blood-derived hematopoietic progenitor cells (HPC) on NK cell differentiation and function." (PMID 34630413, 2021). "Together, the ChIP‐seq and EOMES overexpression results suggesting that the EOMES might directly bound and repressed the expression of inhibitory receptors, and this repression might benefit the T‐cell‐mediated immune response on tumour cells." (PMID 33325636, 2021). "Prior research underscores EOMES's role in CD8+ T cell differentiation and anti-tumor immunity 28-31." (PMID 40520886, 2025).
tumor (continued). "In contrary we found upregulated (EOMES, TNFSFR9, TIGIT, KLRD1) and downregulated genes (PAG1, GNLY, ANXA1, FGFBP2) that are involved in tumor escape from immune surveillance by suppressing T-cells or by reprogramming T-cells toward T-cell exhaustion." (PMID 40079005, 2025). "To assess the activation status of CD8 + cells, we assessed the effector transcription factors eomesodermin (EOMES) and T-bet, which are crucial for anti-tumor T cell responses." (PMID 40465005, 2025). "While Group 3 tumors mainly expressed photoreceptor markers, Group 4 tumor cells expressed mainly UBC markers, including EOMES, OTX2, NNAT, and LMX1A consistent with their proposed cells of origin." (PMID 39659836, 2024). "TF factor motif analysis within H3K27ac peaks revealed 29 MG63-specific TF binding sites, including those for EOMES, PRDM1, EPAS1 (HIF2A), E2F6, and MYC/MAX, which reflect known early development, tumor-initiation, and stemness factors (Worksheet 1)." (PMID 37228489, 2023). "The deletion of EOMES and T-BET led to functional, proliferative, and signaling defects that resulted in an impaired response against tumor cells in vivo." (PMID 37279078, 2023). "In conclusion, whereas both ectopic T-BET and EOMES overexpression in ILC3s completely block IL-22 secretion, only T-BET overexpression increases IFN-γ secretion as well as cytotoxicity against tumor target cells." (PMID 36330517, 2022). "In our samples, the mRNA levels of CCL5, FASLG, EOMES, and PDCD1 in tumor tissues were significantly higher than those in normal tissues." (PMID 34531849, 2021). "Further phenotypic dissection of the CD8+TILs from mouse tumor models reveals that an exhausted phenotype is presented with an increased expression of TIGIT, PD-1, Tim-3, Lag-3, CD101, CD38, and eomesodermin (Eomes) in CD226loCD8+TILs." (PMID 33670993, 2021). "Studies investigating CD8-mediated tumor immunity demonstrate that mTOR controls memory CD8+ T cell differentiation by regulating two transcription factors, T-bet and Eomesodermin (Eomes)." (PMID 27242787, 2016). "Six genes were selected as tumor suppressor gene candidates, among which, ECM1, ATF5 and EOMES are confirmed via siRNA experiments to have potential anti-cancer functions." (PMID 25517360, 2014). "The T-box transcription factor eomesodermin (EOMES) has been found to have a regulatory role for CD8 T cell activity in humans and plays a critical role in tumor immune surveillance and eradication." (PMID 25517360, 2014). "Although more CD8 T cells were detected in tumors (not significant), these cells were characterized by significantly higher expression of exhaustion markers (such as EOMES and LAG3), indicating that tumor‐derived T cells had become exhausted during tumorigenesis." (PMID 40019403, 2025). "Further analysis of tumor-infiltrating CD8+ T cells revealed a less exhausted phenotype, with a significant reduction in the fraction of Tim3+, LAG3+, Blimp1+, and EOMES+ as well as annexin V+ CD8+ T cells, but with a modest increase in T-bet+ cells (P = 0.1878) and CD44+CD8+ T cells." (PMID 38038129, 2023). "We stained the tumor-infiltrating CAR T cells for TCF1, TBET, EOMES, GATA3, ID2, ID3 and IRF4." (PMID 37945901, 2023). "NK cells lacking both T-BET and EOMES also had reduced degranulation to tumor targets after a more prolonged time period following the CRISPR deletion." (PMID 37279078, 2023). "In addition, the activity of TFs such as EOMES and TBX21 were higher in immune cells than in tumor cells, which is consistent with the role of these TFs in driving lymphocyte differentiation." (PMID 36155797, 2022). "Further evidence that IR-780 induced a more pronounced effector phenotype was attained by the assessment of multiple CTL effector markers through real-time qPCR of the whole tumor mRNA, demonstrating increased expression of IFN-γ, TNF-α, Granzyme B, EOMES, Perforin, BLIMP-1, FOXO3, and CXCL10." (PMID 31781498, 2019).
tumor (continued). "NK cells and ILC1 express the transcription factors Eomesodermin (EOMES) and T-box transcription factor 21 (T-BET), which drive the production of interferon (IFN)-γ and cytotoxic molecules such as granzymes and perforin, key features involved in the elimination of virus-infected and tumor cells." (PMID 34885076, 2021). "In bortezomib-treated 4T1HA tumor-bearing mice, CD4+T-cells showed increased IL-2 production, CD11c+ dendritic cells showed increased IL-12 and IL-15 production, and HA-specific activated CD8+T-cells showed enhanced expression of IFNγ, granzyme-B and transcription factor eomesodermin." (PMID 28052005, 2017). "Moreover, activated NK cells could mediate apoptosis of tumor cells through the expression of transcription factors TBX21 and EOMES, factors that can regulate the high expression of cytokines (e.g., IFN-γ and TNF-α) and exert anti-tumor effects through immunomodulatory effects." (PMID 39076970, 2024). "Then, we compared the expression of TBX21, EOMES, IFN-γ, and GZMM in the ESCA tumor tissue among the NICT, NCT, and NONE groups by immunofluorescent staining and qRT-PCR." (PMID 39076970, 2024). "Next, we characterised populations of SPG isolated from adult WT and Inha KO ‘normal’ testes (without visible tumours) by intracellular staining for PLZF, KIT and EOMES by flow cytometry." (PMID 37564373, 2023).
cancer (15 papers, 2011 to 2025). A tumor composed of atypical neoplastic, often pleomorphic cells that invade other tissues. "Cytotoxic CD4+ T cells have been identified in cancers and associated with GZMB and Perforin (PRF) expression via the transcription factor EOMES." (PMID 40492347, 2025). "In particular, we identified three new genes (ECM1, ATF5, and EOMES) with potential anti-cancer functions that may promote the understanding of the molecular mechanisms of HCC development and progression and potentiate the future clinical applications of 5hmC detection." (PMID 25517360, 2014). "Based on regulon-level analysis of single-cell RNA-sequencing data, we found significantly lowered activity of the T-box TFs T-box 21 (TBX21) and eomesodermin (EOMES) in circulating CD8+ T cells and NK cells of the cancer-free TET2delA carriers." (PMID 30890702, 2019). "Using the less stringent criteria in the age analysis to identify subsets with trends, cancer patients showed increases in T box expressed in T cells (Tbet+)CD8+ and eomesodermin (EOMES)+CD8+, as well as Tbet+CD4+ cells." (PMID 28936253, 2016). "Many of these genes function in inflammation (CXCR3, EOMES, IL18R1, GZMM, IL2rb), metastases (CXCR3, BUB1), poor outcome cancers (EOMES, BUB1), or stem cells (EOMES, BUB1)." (PMID 22053823, 2011). "In addition, a subset of these genes have been identified as markers for poor outcomes in lymphoid and other cancers (CXCR3, EOMES, BUB1)." (PMID 22053823, 2011).
infection (12 papers, 2015 to 2025). The state of being infected such as from the introduction of a foreign agent such as serum, vaccine, antigenic substance or organism. "In this study, we evaluated the expressions of different TFs (T-bet, GATA3, FOXP3, and EOMES) through RT-qPCR and the associated cytokine profiles during infection with PRRSV-1 strains of different virulence in target organs." (PMID 34956200, 2021). "GFI1hiCD8+ T cells showed increased expression of TCF1 and EOMES compared to GFI1loCD8+ T cells at day 7 post LCMVArm or LCMVc13 infection." (PMID 40374731, 2025). "Eomesodermin (Eomes), a key transcription factor associated with the cytolytic activity of CD4+ T cells was expressed at similar levels by CD38+ and CD38- CD4+ T cells prior to infection." (PMID 27662621, 2016). "In contrast, the eomesodermin (EOMES) gene is overexpressed, and nucleoside diphosphate kinase A (NME1), polycystic kidney disease 1-like 3 (PKD1L3), as well as nanos homolog 1 (NANOS1) are down-regulated in the infection group." (PMID 38474155, 2024). "Animals belonging to both infected groups, but mainly those infected with the virulent Lena strain, showed upregulation of the TFs T-bet, EOMES, and FOXP3, together with an increase of the cytokine IFN-γ in target organs at the end of the study (approximately 2 weeks post-infection)." (PMID 34956200, 2021). "Furthermore, several additional transcripts associated with innate effector cell function were upregulated throughout acute infection, compared to pre-infection, including NKG7, KLRD1, EOMES, CD160, SLAMF5, and IL12RB1." (PMID 31937782, 2020).
EOMES also shares sentences with these, for which no sentence is quoted: polymicrogyria (5 papers); viral infection (4); ZIKV infection (3); Anxiety (2); autism (2); Cirrhosis (2); HCMV infection (2); amyotrophic lateral sclerosis (1); androgenetic alopecia (1); Ataxia (1); autoimmune disease (1); B cell lymphoma (1); cognitive deficits (1); coronary heart disease (1); gastric cancer (1); heart disease (1); Hepatitis C Infection (1); Hodgkins lymphoma (1); Hypoglycemia (1); Intellectual disability (1); Primary microcephaly (1); Sandhoff disease (1); tuberculosis (1).